FTSJ1 (FtsJ RNA 2'-O-methyltransferase 1)
Description:
Methylates the 2'-O-ribose of nucleotides at positions 32 and 34 of the tRNA anticodon loop of substrate tRNAs. Requisite for faithful cytoplasmic translation. Requires THADA for methylation of the nucleotide at position 32 of the anticodon loop of substrate tRNAs. Requires WDR6 for methylation of the nucleotide at position 34 of the anticodon loop of substrate tRNAs. Promotes translation efficiency of the UUU codon. Plays a role in neurogenesis. Required for expression of genes involved in neurogenesis, mitochondrial translation and energy generation, and lipid biosynthesis. Requisite for RNA-mediated gene silencing. May modify position 32 in tRNA(Arg(ACG)), tRNA(Arg(CCG)), tRNA(Arg(UCG)), tRNA(Cys(GCA)), tRNA(Cys(ACA)), tRNA(Gln(CUG)), tRNA(Gln(UUG)), tRNA(Gly(CCC)), tRNA(Leu(CAG))/tRNA(Leu(CAA)), tRNA(Leu(A/IAG)), tRNA(Leu(UAG)), tRNA(Phe(GAA)), tRNA(Pro(AGG))/tRNA(Pro(CGG))/tRNA(Pro(UGG)) and tRNA(Trp(CCA)), and position 34 in tRNA(Phe(GAA)), tRNA(Leu(CAA)), tRNA(Sec(UCA)), and tRNA(Trp(CCA)).
Synonyms: JM23; CDLIV; SPB1; TRM7; TRMT7; MRX44; MRX9; XLID9
Tractability: PROTAC: ubiquitination databases record sites on it.
Gene: Protein-coding gene on chromosome X (48,476,021 to 48,486,364, forward strand). Ensembl gene ENSG00000068438.
Subcellular location: Cytoplasm; Nucleus
Subcellular location (Human Protein Atlas): Cytosol
Pathways (Reactome):
Metabolism of RNA: tRNA modification in the nucleus and cytosol
Gene Ontology:
Molecular function: protein binding; S-adenosyl-L-methionine binding; tRNA (cytidine(32)-2'-O)-methyltransferase activity; tRNA (guanine) methyltransferase activity; tRNA (guanosine(34)-2'-O)-methyltransferase activity; methyltransferase activity; S-adenosylmethionine-dependent methyltransferase activity; tRNA methyltransferase activity
Biological process: cytoplasmic translation; neurogenesis; tRNA methylation; tRNA nucleoside ribose methylation; wobble position ribose methylation; tRNA modification; tRNA processing
Cellular component: cytoplasm; cytosol; nucleus
Gene-disease validity (ClinGen):
ClinGen rates the evidence that FTSJ1 causes each of these diseases.
X-linked complex neurodevelopmental disorder (X-linked): Definitive. A complex neurodevelopmental disorder that is transmitted via X-linked inheritance, and is characterized by intellectual disability, autism and epilepsy.
Homologues: Orthologues: chimpanzee FTSJ1 (100% identical), macaque FTSJ1 (95% identical), dog FTSJ1 (93% identical), pig FTSJ1 (92% identical), rabbit FTSJ1 (91% identical), guinea pig FTSJ1 (90% identical), rabbit FTSJ1 (87% identical), mouse Ftsj1 (87% identical), rabbit FTSJ1 (86% identical), rat Ftsj1 (86% identical), zebrafish ftsj1 (69% identical), Caenorhabditis elegans R74.7 (52% identical), and 2 more. Paralogues in human: FTSJ3 (38% identical), MRM2 (21% identical).
Diseases named in the same sentence as FTSJ1 in open-access papers:
FTSJ1 is named in the same sentence as 20 diseases in open-access papers, as found by Europe PMC text mining. Sharing a sentence is not in itself a finding about the gene and the disease. The quoted sentences say what the papers report.
Intellectual disability (9 papers, 2013 to 2025). "FTSJ1 plays an important role in brain development and mutation of FTSJ1 is related to intellectual disability." (PMID 38339348, 2024). "Mutations in FTSJ1 are associated with mental retardation and mutations in NSUN2 with intellectual disability as well as cardiac diseases, indicating their importance in human development and health." (PMID 28282871, 2017). "In addition, we performed a transcriptome analysis in these FTSJ1-depleted cells and found that several genes previously associated with intellectual disability (ID) and cancers were deregulated." (PMID 36720500, 2023). "Here, we report a novel FTSJ1 pathogenic variant from an X-linked intellectual disability patient." (PMID 36720500, 2023). "In humans, mutations in the X-chromosomal FTSJ1 gene (FTSJ1, MIM #300499) have been repeatedly found to cause non-syndromic intellectual disability (ID)." (PMID 36101392, 2022). "Inactivation of the X-linked gene FTSJ1, another RNA methyltransferase and ortholog of yeast TRM7, gives rise to non-syndromic intellectual disability." (PMID 24204302, 2013). "Notably, a novel missense allele of FTSJ1 (A26P) associated with intellectual disability reduces the frequency of Nm32, but not Nm3422." (PMID 40483304, 2025).
X-linked intellectual disability (7 papers, 2017 to 2025). An X-linked intellectual deficiency in which not enough information is known, reported or published to indicate whether a gene causes non-syndromic or syndromic presentations. "In fact, defects in tRNA anticodon 2′-O-methylation are implicated in nonsyndromic X-linked intellectual disability due to mutations in FTSJ1." (PMID 30621251, 2019). "FTSJ1 mutations are linked to nonsyndromic X-linked intellectual disability, a genetically and clinically heterogeneous group of brain disorders." (PMID 30477220, 2018). "Mutations in human FTSJ1, the Trm7 homolog, are present in two genetically-independent cell lines of patients and cause non-syndromic X-linked intellectual disability (NSXLID)." (PMID 28208788, 2017). "FTSJ1 mutations are associated with non-syndromic X-linked intellectual disability." (PMID 40483304, 2025). "We propose that TRM7 is important to prevent constitutive GAAC activation throughout eukaryotes, including metazoans, which may explain non-syndromic X-linked intellectual disability associated with human FTSJ1 mutations." (PMID 29596413, 2018). "Moreover, although deficiency of FTSJ1 has been correlated to X-linked intellectual disability and a genetically heterogeneous group of brain disorders, the effects of FTSJ1 deficiency on other organs rather than on brain function have not been investigated." (PMID 32393790, 2020). "Patient cell lines bearing disease-causing FTSJ1 mutations display 2′-O-methylation hypomodification at the anticodon loop of tRNAPhe, providing evidence that FTSJ1 also catalyzes this modification in humans and that lack of Gm34 may be a trigger for X-linked intellectual disability." (PMID 30477220, 2018). "In yeast lack of Trm7-modified tRNAPhe activates the general amino acid control starvation response, whereas specific mutant lesions of the human ortholog FTSJ1 are linked to non-syndromic X-linked intellectual disability." (PMID 30838029, 2019).
breast carcinoma (2 papers, 2021 to 2024). "Overall, FTSJ1 has been poorly and ambivalently studied in cancer, and the role of FTSJ1 in the development of breast cancer and related TME is unknown." (PMID 38339348, 2024).
hepatocellular carcinoma (2 papers, 2019 to 2020). A malignant tumor that arises from hepatocytes.
liver cancer (2 papers, 2024). An epithelial or non-epithelial malignant neoplasm that arises from the liver.
lung carcinoma (2 papers, 2021 to 2022). "Notably, in recent studies, it has been found that tRNA modification was regulated by FTSJ1 in lung cancer, which had a tumor-suppressor effect." (PMID 34660690, 2021). "Collectively, the tRNA-modifying enzymes FTSJ1 and hTRM9L act as tumor suppressors, and measures that can promote their overexpression may be effective in treating lung cancer." (PMID 34660690, 2021). "Evidence revealed that DRAM1 could be a target of FTSJ1 and facilitate lung cancer progression." (PMID 35529878, 2022).
autosomal recessive intellectual disability (1 paper, 2025). "NSUN2 is known to cause forms of autosomal recessive intellectual disability (AR ID) as are methyltransferases from other modification systems, e.g. FTSJ1, a human tRNA 2′-O-methyltransferase, and METTL5, an N6 adenine DNA and rRNA writer." (PMID 39499421, 2025).
breast tumor (1 paper, 2024). "We then examined FTSJ1 protein levels in 120 human primary breast tumor specimens by IHC staining." (PMID 38339348, 2024).
intellectual disability syndromes (1 paper, 2025). "FTSJ1 has also been implicated in neuronal development, and mutations in this gene are associated with intellectual disability syndromes, suggesting that Am modification may be critical for neurodevelopmental gene regulation." (PMID 40870000, 2025).
lung adenocarcinoma (1 paper, 2025). A carcinoma that arises from the lung and is characterized by the presence of malignant glandular epithelial cells. "This study investigates the significance and potential mechanisms of novel mitochondrial autophagy-related biomarkers COASY, FTSJ1, and MOGS in lung adenocarcinoma (LUAD)." (PMID 40313958, 2025).
non-small cell lung carcinoma (1 paper, 2024). A group of at least three distinct histological types of lung cancer, including non-small cell squamous cell carcinoma, adenocarcinoma, and large cell carcinoma. "FTSJ1 downregulation enhanced glycolytic metabolism of non-small cell lung cancer (NSCLC) cells, as indicated by increased levels of lactate, pyruvate, and extracellular acidification rate (ECAR)." (PMID 39695074, 2024).
triple-negative breast carcinoma (1 paper, 2024). An invasive breast carcinoma which is negative for expression of estrogen receptor (ER), progesterone receptor (PR), and human epidermal growth factor receptor 2 (HER2). "In this study, we found that high FTSJ1 expression in triple-negative breast cancer patients was associated with poor prognosis and was associated with reduced infiltration of CD8+T cells in the tumor microenvironment." (PMID 38339348, 2024). "By knocking down FTSJ1, we observed an inhibitory effect on the proliferation and migration of triple-negative breast cancer, while inducing apoptosis and increasing the sensitivity of TNBC cells to T-cell-mediated cytotoxicity." (PMID 38339348, 2024).
tumor (11 papers, 2019 to 2025). "Nevertheless, the association between tumor cells exhibiting high FTSJ1 expression and CD8+ T cells, along with the molecules participating in T cell differentiation, remains unclear at the human tissue level." (PMID 38339348, 2024). "Based on research into COASY, FTSJ1, and MOGS, this study investigates their associations with immune cell infiltration and the tumor microenvironment, aiming to identify novel targets and strategies for personalized LUAD treatment." (PMID 40313958, 2025). "FTSJ1, an enzyme involved in tRNA modification, has been shown to be overexpressed in various cancers, correlating with tumor malignancy." (PMID 40313958, 2025). "The knockdown of FTSJ1 resulted in a significant reduction in both tumor volume (p < 0.0001) and weight (p < 0.0001) compared to tumors derived from unmodified 4T1 cells." (PMID 38339348, 2024). "In consistent with the results from in vitro experiments, FTSJ1 protein expression levels in NSCLC tumor tissues were negatively correlated with that of PGK1." (PMID 39695074, 2024). "Taken together, our data suggests that lower FTSJ1 expression level in tumor tissues reflects higher glycolysis metabolism in NSCLC." (PMID 39695074, 2024). "In human NSCLC tumor samples, FTSJ1 expression was negatively correlated with PGK1 expression level and the SUVmax value of PET/CT scan." (PMID 39695074, 2024). "We found that the proportion of CD8+/CD3+ T cells in the tumor tissue increased from 14.5% to 22.3% after Ftsj1 knockdown (p < 0.05)." (PMID 38339348, 2024). "Lastly, SPARC and more recently FTSJ1 gene product activities were proposed to be involved in both metastasis and tumour suppression." (PMID 36720500, 2023). "It has been shown that FTSJ1 have a tumor-suppressor effect in healthy cells, but was downregulated in non-small cell lung cancers." (PMID 35721477, 2022). "Further research showed that the amount of Am in tRNAs was significantly related to the expression of FTSJ1, which exerted significant tumor suppressor ability via interacting with DNA damage-regulated autophagy modulator 1 (DRAM1)." (PMID 34660690, 2021). "Twenty-one days later, the growth rate, tumor size, and tumor weight in FTSJ1-overexpression group were obviously lower than those in NC group." (PMID 32393790, 2020). "Our findings suggested an important mechanism of tRNA modifications in NSCLC and demonstrated novel roles of FTSJ1 as both tRNA Am modifier and tumor suppressor in NSCLC." (PMID 32393790, 2020). "Here, we found that FTSJ1 correlated to Am modification levels and suppressed tumor growth in NSCLC." (PMID 32393790, 2020). "Similarly, the RNA modification-related genes DHX35, DHX8, ENY2, and FTSJ1 also upregulated in most tumor tissues." (PMID 40041484, 2025). "In this study, we establish that FTSJ1 acts as a tumor promotor, is involved in cancer immune evasion, and may serve as a potential immunotherapy target in TNBC." (PMID 38339348, 2024). "Our study suggests that FTSJ1 may regulate the expression of CD276, which partly explains the effect of FTSJ1 on tumor and tumor immunity." (PMID 38339348, 2024). "Furthermore, the high expression of FTSJ1 in TNBC attenuates CD8+T cell infiltration in the tumor microenvironment (TME) correlated with poorer prognosis for clinical TNBC patients." (PMID 38339348, 2024). "FTSJ1 acts as a tumor promotor, is involved in cancer immune evasion, and may serve as a potential immunotherapy target in TNBC." (PMID 38339348, 2024). "We revealed that FTSJ1 possessed tumor suppressive capacity in vitro and in vivo." (PMID 32393790, 2020). "Collectively, multiple lines of evidence indicated that FTSJ1 may exert a tumor suppressor function partly through interacting with DRAM1 in NSCLC." (PMID 32393790, 2020). "Our findings suggested that FTSJ1 might function as a tumor suppressor in NSCLC." (PMID 32393790, 2020).
tumor (continued). "To investigate the relationship between FTSJ1 and tumor-infiltrating CD8+ T cells in vivo, we inoculated control and Ftsj1 KD 4T1 cells into immunocompetent Bal/bc mice." (PMID 38339348, 2024). "IHC analysis showed that Ki-67 expression in FTSJ1-overexpression group was lower than that in NC group; whereas TUNEL staining revealed that FTSJ1-overexpression tumor tissues had more apoptotic cells that that in tumors of NC froup." (PMID 32393790, 2020). "The results showed that the expression levels of seven tRNA-modifying genes (FTSJ1, ADAT1, U13, RNMTL1, TRDMT1, METTL14, and TRMT1L) in NSCLC tumor tissues were significantly lower than that in normal tissues (all P values < 0.05)." (PMID 32393790, 2020). "To assess the clinical significance of FTSJ1 in glucose metabolism in NSCLC, we investigated the relationship between SUVmax value (a surrogate indicant for aerobic glycolysis) of PET-CT scan and the expression levels of FTSJ1 and PGK1 proteins in tumor tissues resected from 19 NSCLC patients." (PMID 39695074, 2024). "Consequently, in tumor cells after co-culture, we found that mRNA expression of CD274 was significantly downregulated in FTSJ1 KD cell lines and upregulated in FTSJ1 OE cell lines compared to the control cell line." (PMID 38339348, 2024). "In addition, rescue assays demonstrated that the tumor suppressive effect of FTSJ1 depended on DRAM1 expression, as co-transfection of FTSJ1 and si-DRAM1 into NSCLC cells significantly enhanced the tumor suppressive effect of FTSJ1 on cell proliferation." (PMID 32393790, 2020). "In addition, the proportions of CD4+T cells showed no significant changes in the tumor tissue in the Ftsj1 KD group compared with the control group." (PMID 38339348, 2024).
cancer (10 papers, 2020 to 2025). A tumor composed of atypical neoplastic, often pleomorphic cells that invade other tissues. "The protein encoded by FTSJ1 plays a crucial role in rRNA modification, and its overexpression has been associated with increased aggressiveness and poor prognosis in various cancers." (PMID 40313958, 2025). "Taken together, these results show deregulation of some mRNAs linked to cancer and brain functioning in FTSJ1 affected individuals’ blood-derived LCLs." (PMID 36720500, 2023). "In conformity, the decreased expression of FTSJ1, as we found, was also associated to the inhibition of apoptosis in cancer." (PMID 33968923, 2021). "As some of the FTSJ1-deregulated miRNAs and mRNAs were implicated in similar biological processes such as cancer and brain function, we wondered whether there were some miRNA::mRNA pairs that could be involved in these commonly deregulated processes." (PMID 36720500, 2023). "To define the role of FTSJ1 in cancer, we analyzed the RNA-seq data collected from the TCGA database, and we found that the expression of FTSJ1 was significantly upregulated in BRCA as compared with their adjacent normal tissues." (PMID 38339348, 2024). "The knockdown of FTSJ1 inhibits TNBC cell proliferation and development, induces apoptosis of cancer cells, and increases the sensitivity of TNBC cells to T-cell-mediated cytotoxicity." (PMID 38339348, 2024). "In summary, our study demonstrates that the knockdown of FTSJ1 in TNBC cells not only suppresses the proliferation and migration and induces apoptosis of cancer cells but also increases the sensitivity of TNBC cells to T-cell-mediated cytotoxicity." (PMID 38339348, 2024). "Additionally, the outcome of the T-cell-mediated cancer cell killing assay (without T cells group, E:T ratios = 0:1) can infer that FTSJ1 plays an oncogenic role in TNBC." (PMID 38339348, 2024).
infection (2 papers, 2023 to 2024). The state of being infected such as from the introduction of a foreign agent such as serum, vaccine, antigenic substance or organism. "Viral NS5, but not host FTSJ1, increased f5Cm levels late in infection." (PMID 37986976, 2023).
neurodevelopmental disorder (2 papers, 2020 to 2023). A behavioral and cognitive disorder with onset during the developmental period that involves impaired or aberrant development of intellectual, motor, or social functions. "Importantly, CG33172, TRM734 and WDR6 are members of the WD40-repeat-containing domain superfamily that contains also the human protein WDR4, another tRNA-MTase cofactor that, like FTSJ1, when mutated is associated with neurodevelopmental disorders." (PMID 31943105, 2020). "Similarly, in humans, several mutations in FTSJ1 were shown to be causative of a neurodevelopmental disorder known as Non-Syndromic X-linked Intellectual Disability (NSXLID)." (PMID 31943105, 2020). "Next, we sought for possible links between the 36 significantly deregulated miRNAs in FTSJ1 mutant cells and neuronal functions or neurodevelopmental disorders." (PMID 36720500, 2023).
FTSJ1 also shares sentences with these, for which no sentence is quoted: atherosclerosis (1 paper); demyelinating disease (1); non-syndromic X-linked intellectual disability (1); pancreatic tumors (1).